VDAC2 (voltage dependent anion channel 2)
Description:
Non-selective voltage-gated ion channel that mediates the transport of anions and cations through the mitochondrion outer membrane and plasma membrane. The channel adopts an open conformation at zero mV and a closed conformation at both positive and negative potentials. There are two populations of channels; the main that functions in a lower open-state conductance with lower ion selectivity, that switch, in a voltage-dependent manner, from the open to a low-conducting 'closed' state and the other that has a normal ion selectivity in the typical high conductance, 'open' state. Binds various lipids, including the sphingolipid ceramide, the phospholipid phosphatidylcholine, and the sterols cholesterol and oxysterol. Binding of ceramide promotes the mitochondrial outer membrane permeabilization (MOMP) apoptotic pathway. Associates with the translocase of the outer mitochondrial membrane (TOM) complex and PINK1 kinase at depolarized mitochondria, this interaction stabilizes PINK1 at the outer mitochondrial membrane and triggers downstream mitophagy by the recruitment of the E3 ubiquitin ligase PRKN. Catalyzes the scrambling of phospholipids across the outer mitochondrial membrane; the mechanism is unrelated to channel activity and is capable of translocating both anionic and zwitterionic phospholipids.
Tractability: Small molecule: a structure with a bound ligand is known. Antibody: UniProt predicts a signal peptide or a membrane-spanning region. PROTAC: UniProt records ubiquitination sites on it; ubiquitination databases record sites on it; its protein half-life has been measured; a small molecule that binds it is known.
Target class: Ion channel; Mitochondrial and plastid porin family; Other ion channel; Voltage-dependent anion-selective channel
Gene: Protein-coding gene on chromosome 10 (75,209,983 to 75,231,456, forward strand). Ensembl gene ENSG00000165637.
Subcellular location: Mitochondrion outer membrane; Membrane
Subcellular location (Human Protein Atlas): Mitochondria
Pathways (Reactome):
Autophagy: PINK1-PRKN Mediated Mitophagy
Metabolism of proteins: Ub-specific processing proteases
Transport of small molecules: Mitochondrial calcium ion transport
Gene Ontology:
Molecular function: ceramide binding; cholesterol binding; phosphatidylcholine binding; phospholipid scramblase activity; protein binding; voltage-gated monoatomic anion channel activity; voltage-gated monoatomic ion channel activity; oxysterol binding
Biological process: binding of sperm to zona pellucida; mitochondrial outer membrane permeabilization; mitochondrial transmembrane transport; monoatomic anion transport; phospholipid translocation; monoatomic anion transmembrane transport; plasma membrane phospholipid scrambling; transmembrane transport
Cellular component: acrosomal vesicle; membrane; mitochondrial membrane; mitochondrial nucleoid; mitochondrial outer membrane; mitochondrion; nucleus; sperm midpiece
Genetic constraint (gnomAD): Loss-of-function variants: 4 observed, 33.36 expected, observed/expected ratio (o/e) 0.12, 90% interval 0.058 to 0.27. The upper end of that interval is the gene's LOEUF score, 0.27, which puts it in group 1 of 6, group 1 being the genes least tolerant of losing a copy. Missense variants: 225 observed, 326.96 expected, observed/expected ratio (o/e) 0.69, 90% interval 0.62 to 0.77. Synonymous variants: 103 observed, 116.73 expected, observed/expected ratio (o/e) 0.88, 90% interval 0.75 to 1.04.
Homologues: Orthologues: guinea pig VDAC2 (99% identical), dog VDAC2 (96% identical), macaque VDAC2 (96% identical), rat Vdac2 (95% identical), mouse Vdac2 (94% identical), rabbit VDAC2 (86% identical), tropical clawed frog vdac2 (84% identical), rat AABR07051831.1 (84% identical), chimpanzee VDAC2 (80% identical), zebrafish vdac2 (80% identical), Drosophila melanogaster porin (59% identical), Caenorhabditis elegans vdac-1 (39% identical), and 3 more. Paralogues in human: VDAC1 (72% identical), VDAC3 (71% identical).
Diseases named in the same sentence as VDAC2 in open-access papers:
VDAC2 is named in the same sentence as 75 diseases in open-access papers, as found by Europe PMC text mining. Sharing a sentence is not in itself a finding about the gene and the disease. The quoted sentences say what the papers report.
melanoma (20 papers, 2015 to 2025). A malignant, usually aggressive tumor composed of atypical, neoplastic melanocytes. "In melanoma cells, the downregulation of Nedd4 by shRNA rescues the elimination of VDAC2/3 proteins induced by erastin and increases the sensitivity of melanoma cells to erastin, thereby regulating ferroptosis in melanoma cells." (PMID 40509137, 2025). "The specific mechanism was identified as Nedd4‐mediated ubiquitination of VDAC2/3 in melanoma, which plays a crucial role in ferroptosis." (PMID 38634270, 2024). "Previous studies have reported that VDAC2 can regulate the ferroptosis sensitivity of melanoma cells." (PMID 37496319, 2023). "For example, knockdown of Nedd4 inhibits VDAC2/3 protein degradation, thereby increasing the sensitivity of melanoma cells to the ferroptosis inducer erastin." (PMID 36399105, 2022). "NEDD4 was reported to degrade VDAC2/3 via the UPS to inhibit the sensitivity of melanoma cells to erastin." (PMID 34869326, 2021). "The depletion of NEDD4 was found to promote the ferroptosis induced by erastin by limiting the degradation of VDAC2/3 in melanoma." (PMID 34277151, 2021). "The observed effects of Nedd4 on the protein degradation of VDAC2/3 suggest that the expression level of Nedd4 should modulate erastin sensitivity in melanoma cells." (PMID 31974380, 2020). "Taken together, these results support the idea that Nedd4 and VDAC2/3 play essential roles in regulating erastin-induced ferroptosis in different subtypes of melanoma cells." (PMID 31974380, 2020). "Collectively, our data illustrate that erastin triggers ubiquitin–proteasomal degradation of VDAC2/3 in melanoma cells." (PMID 31974380, 2020). "Knockdown of Nedd4 leads to elevated protein level of VDAC2/3, which increased the sensitivity of melanoma cells to erastin both in vitro and in vivo." (PMID 31974380, 2020). "Collectively, these findings suggest that FOXM1 inhibits ferroptosis by regulating Nedd4 expression and subsequent VDAC2/3 degradation in melanoma cells." (PMID 31974380, 2020). "As demonstrated in melanoma cells, overexpressing Bcl-xS disrupts the VDAC2-Bak interaction by binding to VDAC2, releasing Bak, and allowing it to initiate apoptosis." (PMID 26090338, 2015). "Voltage dependent anion channel 2 (VDAC2) can inhibit iron sagging in melanoma." (PMID 39311766, 2024). "While STARD1 is not directly regulated by ubiquitination it is stabilised by VDAC2, a protein in the outer mitochondrial membranate that is ubiquitinated by Nedd4 in melanoma cells, a HECT E3 ligase with high sequence homology in the interacting WW domains to Itch." (PMID 38216558, 2024). "In addition, E3 NEDD4 interacts with the PPxY motifs of VDAC2 and VDAC3 via its WW domain, thereby mediating K48-linked ubiquitination and degradation of VDAC2 and VDAC3 in melanoma cells." (PMID 36147464, 2022). "In A375 melanoma cell lines, erastin, a ferroptosis activator, stimulates NEDD4 and FOXM1 expression, and it led to the ubiquitination and degradation of voltage-dependent anion channels, VDAC2/3, which further led to the suppression of erastin-induced ferroptosis in melanoma." (PMID 36293239, 2022). "In A375 melanoma cell lines, erastin, a ferroptosis activator, stimulates the expression of NEDD4 and FOXM1 that leads to the ubiquitination and degradation of voltage-dependent anion channels, VDAC2/3, which further leads to the suppression of erastin-induced ferroptosis in melanoma." (PMID 36293239, 2022). "We further examined whether knockdown of VDAC2/3 suppresses erastin-induced ferroptosis in melanoma cells." (PMID 31974380, 2020). "Moreover, aberrant VDAC2 expression or functioning has been reported in multiple tumors, including melanoma, epithelial thyroid tumors, and breast cancer, indicating that targeting VDAC2 is of therapeutic significance for cancer treatment." (PMID 30250190, 2018). "A basic study about melanoma demonstrated VDAC2 could suppress ferroptosis." (PMID 33954048, 2021).
melanoma (continued). "The broad-spectrum DUB inhibitor palladium pyrithione was also able to induce ferroptosis by promoting GPX4 protein degradation in lung cancer cells, while erastin promoted the UPS-dependent degradation of VDAC2 and VDAC3 during ferroptosis in melanoma cells." (PMID 36358651, 2022). "In melanoma cells, NEDD4 degraded VDAC2/3 via the ubiquitin-proteasome system (UPS) to inhibit the sensitivity to erastin." (PMID 34869326, 2021). "Here we identified VDAC2 and VDAC3 as two substrates of Nedd4 during erastin-induced ferroptosis in melanoma cells." (PMID 31974380, 2020). "In melanoma cells, the FOXM1 could inhibit ferroptosis via regulating the expression of Nedd4 and the degradation of VDAC2/3." (PMID 38382091, 2024). "To test whether Nedd4-mediated VDAC2/3 degradation is also essential for the suppression of erastin-induced ferroptosis in melanoma cells carrying wt BRAF, we knocked down Nedd4 or overexpressed VDAC2/3 in MeWo cells." (PMID 31974380, 2020). "VDAC2 as a voltage-dependent anion channel was widely explored in multiple FRG prognostic models and bound directly with the ferroptosis activator erastin for increasing the sensitivity of cancer cells to ferroptosis via a FOXM1-Nedd4-VDAC2/3 negative feedback loop in melanoma." (PMID 36386203, 2022).
glioma (9 papers, 2018 to 2024). A benign or malignant brain and spinal cord tumor that arises from glial cells (astrocytes, oligodendrocytes, ependymal cells). "High expression of VDAC2 was associated with a longer OS and negatively correlated with glioma grades." (PMID 33594759, 2021). "Indeed, our results showed that high level of VDAC2 expression was associated with better prognosis of patients with gliomas." (PMID 30250190, 2018). "PFKP, the nearest protein-coding gene for PFKP-DT, has been reported to interact with VDAC2, thus regulating phenotypic reprograming and glucose metabolism of glioma stem cells." (PMID 38229597, 2024). "In patients, VDAC2 expression was inversely correlated with glioma grades; moreover, patients with VDAC2 expression had better survival than those with low VDAC2 expression." (PMID 38139462, 2023). "For instance, the voltage-dependent anion channel 2 (VDAC2) was downregulated in glioma stem cells (GSC), which have a high glycolytic profile compared to non-stem cell tumor cells (NSTCs)." (PMID 38139462, 2023). "It has been previously demonstrated that PFK inhibitor clotrimazole (CTZ) effectively compromised the ability of voltage-dependent anion channel 2 (VDAC2) to induce glioma stem cells phenotypic transition and metabolic phenotypic transition." (PMID 32470015, 2020). "The IHC staining indicated that VDAC2 expression was inversely correlated with glioma grades, which was confirmed by the data from The Cancer Genome Atlas (TCGA) database." (PMID 30250190, 2018). "Our study demonstrates for the first time that VDAC2 is a critical regulator for the metabolic reprogramming of glioma cells through controlling the PFKP-mediated glycolysis." (PMID 30250190, 2018). "Similarly, survival probability in hepatocellular carcinoma was reliably predicted by a glioma prediction model (ACSL3, ACSL6, ACACA, G6PD, SLC1A5, SLC7A11 and VDAC2) and by a risk model with a strong overlap with the genes in the glioma models (G6PD, HMOX1, LOX, SLC7A11, STMN1/Stathmin 1)." (PMID 34926298, 2021). "In conclusion, we demonstrate that VDAC2 is a new glycolytic regulator controlling the phenotype transition between glioma stem cells and non-stem cells and may serves as a new prognostic indicator and a potential therapeutic target for glioma patients." (PMID 30250190, 2018). "For example, voltage-dependent anion channel 2 (VDAC2) regulates glucose metabolism and reprogramming by interacting with PFKP to impair self-renewal and tumorigenic properties of glioma stem cells." (PMID 34638609, 2021). "Notably, although we have demonstrated that VDAC2 is a glycolytic regulator and involves in controlling the phenotype transition between GSCs and NSTCs, the molecular mechanisms of how glycolytic changes regulate the stemness of glioma cells need to be further explored." (PMID 30250190, 2018).
breast carcinoma (5 papers, 2018 to 2024). "Survival analysis of ion channels interacting with EMT-related genes showed KCNN4 (p-value: 0.071), CFTR (p-value: 0.16), KCNJ10 (p-value: 0.17), VDAC1 (p-value: 0.000003) and VDAC2 (p-value: 0.052) the level of expression associated with survival of breast cancer patients." (PMID 35326596, 2022). "Despite the decrease in VDAC1 and VDAC2 mRNA, we observed that mOGT did not affect the levels of VDAC1 and VDAC2 proteins in the mitochondria of normal and breast cancer cells." (PMID 38473405, 2024).
male infertility (5 papers, 2015 to 2024). The inability of the male to effect fertilization of an ovum after a specified period of unprotected intercourse. "Based on previous studies, we suggest that abnormal methylation of the VDAC2 promoter region causes either a decrease in the expression of VDAC2 mRNA or a functional defect, leading to changes in sperm motility and male infertility." (PMID 27892527, 2016). "This research was primarily aimed at analyzing 4 different tagSNPs (rs2804535, rs7896741, rs11001334 and rs1259503) of the VDAC2 gene to determine their relationship with male infertility." (PMID 27806320, 2016). "From these results, one could infer that HADHA in large litter size sperm downregulates VDAC2 to affect male infertility." (PMID 26348888, 2015). "In our study, the SNP rs11001334 (C > T) is a non-coding transcript exon variant located in exon 12 and may affect the transcriptional level of a non-coding RNA, which then may alter the transcription of the VDAC2 gene and may ultimately result in idiopathic male infertility." (PMID 27806320, 2016). "Therefore, this SNP may affect VDAC2 protein function by modulating the splicing efficiency of the VDAC2 gene and may ultimately result in idiopathic male infertility." (PMID 27806320, 2016). "We found that GSTM5 and VDAC2, which were higher in LFS, were involved with spermatogenesis, the acrosome reaction, and male infertility." (PMID 31488871, 2019). "Although it has been suggested that human VDAC2 plays an important role in sperm function and male fertility, there have been no related studies of the hidden role that VDAC2 plays in male infertility, particularly idiopathic male infertility." (PMID 27806320, 2016).
Arrhythmia (4 papers, 2020 to 2025). Any cardiac rhythm other than the normal sinus rhythm. "Decreasing interaction of VDAC2 and TMEM43 in mutant cells may change the cellular localization of VDAC2 and influence mitochondrial Ca2+ uptake, leading to effects like arrhythmia, fibrosis that are found in TMEM43 S358L associated ARVC." (PMID 41411330, 2025). "Knockout of VDAC2 decreased mitochondrial Ca2+ uptake and led to cytosolic Ca2+ overload, resulting in arrhythmia, tachycardia, cardiomyopathy and cardiac fibrosis." (PMID 41411330, 2025). "HF is associated with an increased risk for arrhythmia and efsevin was previously suggested to suppress arrhythmogenesis in cardiomyocytes suggesting a role for VDAC2 also as a protective pathway against arrhythmia." (PMID 34321484, 2021). "Our data provide new insights into VDAC2 function as well as a basis for computer‐aided design of optimized compounds that could serve as research compounds and therapeutics for cardiac arrhythmia." (PMID 32059260, 2020). "Thus, drugs targeting VDAC2 might fulfill a double role by suppressing cardiac arrhythmia and enhancing cardiac function." (PMID 34321484, 2021). "The expression of wild-type VDAC2 but not a mutant in which E73 was mutated to glutamine mediated SR-mitochondria Ca2+ transfer in cardiomyocytes, and the overexpression of wild-type VDAC2, but not E73Q, restored rhythmic cardiac contractions in a zebrafish arrhythmia model." (PMID 36613710, 2022).
asthenospermia (4 papers, 2016 to 2024). "In addition, an abnormal hypermethylation profile of the VDAC2 promoter has been suggested to be a pathogenic factor in cases of idiopathic asthenozoospermia." (PMID 35409285, 2022). "Abnormal methylation of VDAC2 promoter may be a potential cause to idiopathic asthenospermia." (PMID 27892527, 2016). "In human male abnormal hypermethylation of VDAC2 promoter correlated with idiopathic asthenospermia while in complete unmethylation or mild hypermethylation, sperm motility improved confirming the role of VDAC2 expression in human spermatozoa." (PMID 33036380, 2020). "In this study, we explored the different methylation statuses of the VDAC2 gene between normal spermatozoa and asthenospermia." (PMID 27892527, 2016).
cardiomyopathy (4 papers, 2021 to 2025). A disease of the heart muscle or myocardium proper. "Furthermore, conditional ablation of VDAC2 specifically in cardiomyocytes causes cardiomyopathy suggesting an essential role for VDAC2 in maintaining the physiological function of the heart." (PMID 34483974, 2021). "Reintroduction of VDAC2 in 6-week-old knock-out mice partially rescued the cardiomyopathy phenotype." (PMID 34321484, 2021). "Reintroduction of VDAC2 in 6-week-old KO mice using an adeno-associated virus 9 (AAV9) vector seemed to partially rescue the cardiomyopathy phenotype suggesting a plausible role of VDAC2 as a therapeutic target in clinical HF." (PMID 34321484, 2021). "Additionally, reintroduction of VDAC2 in young-KO mice showed a partial rescue of the cardiomyopathy phenotype suggesting the importance of VDAC2 in normal cardiac functioning." (PMID 34321484, 2021). "Furthermore, a heart-specific VDAC2 knockout showed postnatal onset of progressive fibrosis and cardiomyopathy, resulting in early mortality indicating a, presumably cardiac, role of VDAC2, which cannot be fulfilled by the two other isoforms." (PMID 33477936, 2021).
glioblastoma (4 papers, 2018 to 2024). The most malignant astrocytic tumor (WHO grade IV). "In resting glioblastoma cells, Bak was identified as part of three complexes involving proteins from the mitochondrial importation/sorting machinery—namely, VDAC2/Mtx1/Mtx2/Bak, Mtx1/Mtx2/Bak, and Mcl-1/TOM70/Mtx2/Bak." (PMID 35204663, 2022). "Consistent with this hypothesis, deletion of VDAC2 in glioblastoma cells engineered to be BAX-dependent (i.e., ∆BAK) significantly inhibited apoptosis in response to BH3-mimetics." (PMID 30478310, 2018).
hepatocellular carcinoma (4 papers, 2023 to 2024). A malignant tumor that arises from hepatocytes. "Celastrol targets VDAC2 to induce mitochondria-dependent ferroptosis and apoptosis in hepatocellular carcinoma, with liposome-based delivery enhancing its efficacy and reducing side effects." (PMID 39315094, 2024). "In support of this, it has been shown that when 5 L rat hepatoma cells are exposed to pollutants, the expression of VDAC2 increases and this protects the cells." (PMID 38927058, 2024). "Using the human hepatoma HepG2 cell line, it was shown that quinocetone, a toxic chemical, increases cell death when VDAC2 oligomerizes, and DIDS (4′4′-diisothiocyanostilbene-2,2′-disulfonic acid—a blocker of VDAC oligomerization) blocked oligomerization and cell death." (PMID 38927058, 2024).
lung adenocarcinoma (4 papers, 2024). A carcinoma that arises from the lung and is characterized by the presence of malignant glandular epithelial cells. "The study revealed that RRM2, SLC2A1, DDIT4, and VDAC2 were positively associated with the survival risk of lung adenocarcinoma patients." (PMID 39311766, 2024). "For instance, Hedyotis diffusa injection (HDI) has been found to induce ferroptosis in lung adenocarcinoma cells by increasing ROS release through the Bax/Bcl2/VDAC2/3 axis, independently of GPX4 and the PUFA-PLS pathway." (PMID 39944353, 2024).